TGFB1 (transforming growth factor beta 1)
Diseases named in the same sentence as TGFB1 in open-access papers (continued):
Sharing a sentence is not in itself a finding about the gene and the disease.
pulmonary fibrosis (continued). "Calpeptin also suppressed the activation of transforming growth factor β1 (TGFβ1)-Smad2/3 signaling pathway, which plays crucial role in lung fibrosis and EMT." (PMID 29666896, 2018). "Pulmonary fibrosis is characterized by the excessive deposition of collagen and other extracellular matrix proteins within the lung interstitium, which is mediated by transforming growth factor beta 1 (TGF-β1) through its downstream signaling pathway." (PMID 28234907, 2017). "Our results demonstrates that KLF4 plays an important role in bleomycin-induced lung fibrosis through suppressing TGFβ1-induced EMT." (PMID 29158503, 2017). "Effects of PFD treatment were studied in mouse lung fibroblasts (MLF) following induction by transforming-growth factor beta 1 (TGF-β1) and in mice following bleomycin-induced lung fibrosis." (PMID 28420366, 2017). "It is well known that FN and α-SMA are up-regulated by TGFβ-1 and contribute to the pathogenesis of pulmonary fibrosis." (PMID 27604640, 2016). "Transforming growth factor β-1 (TGFβ-1)-induced phosphorylation of transcription factors Smad2 and Smad3 plays a crucial role in the pathogenesis of idiopathic pulmonary fibrosis (IPF)." (PMID 27604640, 2016). "b-AP15, an inhibitor of UCHL5, attenuates TGFβ-1 signaling and diminishes pulmonary fibrosis in a bleomycin-induced pulmonary fibrosis model." (PMID 27604640, 2016). "To further investigate the role of UCHL5 in TGFβ-1 signaling and pulmonary fibrosis, first, we examined the UCHL5 expression in lungs from IPF patients." (PMID 27604640, 2016). "The transforming growth factor β-1 (TGFβ-1) signaling pathway plays a central role in the pathogenesis of pulmonary fibrosis." (PMID 27853171, 2016). "This is the first study to identify that UCHL5 plays a pro-fibrotic role in the pathogenesis of pulmonary fibrosis through stabilization of Smad2/Smad3 and enhance in TGFβ-1 signaling in HLF and a murine model of pulmonary fibrosis." (PMID 27604640, 2016). "This study aimed to examine the effects of CpG ODN1826 on transforming growth factor-beta 1(TGF-β1) and radiation-induced pulmonary fibrosis in mice." (PMID 27190497, 2016). "Here, we demonstrate that UCHL5 de-ubiquitinates and stabilizes Smad2 and Smad3, thereby promoting TGFβ-1 signaling and contributes to the pathogenesis of pulmonary fibrosis." (PMID 27604640, 2016). "For example, integrin αvβ6 has been shown to be important for TGFβ1 activation on lung epithelial cells, and β6 knockout animals or αvβ6 neutralization attenuated pulmonary fibrosis development." (PMID 26867691, 2016). "In accord with these findings, PINK1 expression appeared to be reduced in fibrotic lung tissue from bleomycin and a TGFβ1-adenoviral model of lung fibrosis." (PMID 26059457, 2015). "BMP7 opposes TGFβ1-mediated collagen induction in mouse pulmonary myofibroblasts and inhibits silica-induced lung fibrosis in rats." (PMID 25849157, 2015). "Fibroblast to myofibroblast differentiation (FMD) is an important feature of pulmonary fibrosis in which the profibrotic cytokine TGFβ1 plays a pivotal role." (PMID 26059457, 2015). "Similar results were obtained by Kolodsick, who found that PGE2 inhibits TGFβ1-induced pulmonary fibrosis by an EP2 receptor-activated pathway." (PMID 25327961, 2014). "The observed regulation by TGFβ1 is of particular relevance within the context of several airway diseases, particularly COPD and Idiopathic Pulmonary Fibrosis, in which TGFβ1 is a key driver of fibrosis and extracellular matrix deposition." (PMID 24058608, 2013). "TGFβ1/Smad3 signaling stimulates connective tissue expression and epithelial-mesenchymal transition, events considered key to the development of lung fibrosis." (PMID 22997505, 2012). "Considering its importance in the development of lung fibrosis, research directed at investigating the factors that control TGFβ1/Smad3 signaling has intensified." (PMID 22997505, 2012).
pulmonary fibrosis (continued). "Transforming growth factor beta 1 (TGFβ1) plays a major role in many lung diseases including lung cancer, pulmonary hypertension, and pulmonary fibrosis." (PMID 21625455, 2011). "Increased expression of TGFβ1 or TGFβ2 is seen in early skin lesions and in lung tissue from patients with SSc ILD, and TGFβ1 was significantly elevated in bronchoalveolar lavage fluid from SSc patients with pulmonary fibrosis." (PMID 22013449, 2011). "We next compared classical Ashcroft scoring with micro-CT based evaluation of TGFβ-1 induced lung fibrosis in mice." (PMID 21176193, 2010). "Previous studies have demonstrated TGFβ1 as a key effector cytokine in the development of lung fibrosis." (PMID 17883846, 2007). "The importance of TGFβ1 to the development of lung fibrosis, was however, demonstrated by the lung response to bleomycin." (PMID 17883846, 2007). "This increase in collagen production, coupled with the observed enhanced active TGFβ1 immunostaining in transgenic mice provide further evidence for the pathogenomic role of TGFβ1 in the initiation and progression of lung fibrosis." (PMID 17883846, 2007). "Transforming Growth Factor beta 1(TGF-β1) is a key effector cytokine in the development of lung fibrosis." (PMID 16948840, 2006). "For instance, TGFβ1-induced stress fiber assembly has been documented in MRC-5 lung fibroblasts, where it contributes to increased contractility and extracellular matrix production, both hallmark features of pulmonary fibrosis." (PMID 40299552, 2025). "Furthermore, tectorigenin inhibits pulmonary fibrosis and airway inflammation by modulating the TGFβ1/Smad and TLR4/NFκB signaling pathways, highlighting its potential role in preventing the structural lung changes associated with chronic asthma." (PMID 40598285, 2025). "Another component, bellidifolin (BELDF), was reported to aid in the reduction of α-SMA and Collagen I and III production in myocardial fibrosis and may prove to be a useful treatment for pulmonary fibrosis through TGFβ1 signaling." (PMID 41361355, 2025). "The increase in CDK8 expression may be related to the regulation of miRNA-770, as previous studies have shown an inverse correlation between miRNA-770 expression and CDK8 expression 42, and miRNA-770 is inhibited by TGFβ1 in lung fibrosis." (PMID 39781457, 2025). "TGFB1 is a pro-fibrotic growth factor and a master regulator of lung fibrosis." (PMID 39739031, 2025). "Also, the HER1 ligand amphiregulin and the EGFR signaling pathway are observed in cases with TGFb1-dependent pulmonary fibrosis." (PMID 39062713, 2024). "Diammonium glycyrrhizate played anti-pulmonary fibrosis effects by reducing the secretion of TGFβ1 and connective tissue growth factor in lung tissue, and could reduce chronic lung injury through anti-inflammatory effects." (PMID 38567353, 2024). "It facilitates TGFβ1-induced pulmonary fibrosis by increasing Smad3 acetylation." (PMID 38785963, 2024). "Thus, a recently designed dual inhibitor of HDACs and the PI3K/AKT pathway, CUDC-907, effectively treated bleomycin-TGFβ1-induced lung fibrosis as well as TGFβ1-induced tumor fibrosis." (PMID 38397377, 2024). "Moreover, our mechanistic evaluation indicated that TMEM176B appears to mitigate pulmonary fibrosis by inhibiting the TGFβ1-SMAD signaling pathway." (PMID 39170226, 2024). "Research on TGFβ1 has been a hot topic in various types of pulmonary fibrosis for several years." (PMID 38239077, 2024). "An in vitro fibroblast study also reported that the PDE5 inhibitor vardenafil may improve pulmonary fibrosis via TGFβ1." (PMID 39684311, 2024). "SUZ12 suppresses p27 and p27 promotes TGFB1 mediated pulmonary fibrosis." (PMID 37967122, 2023). "Transforming growth factor-β1 (TGFβ1) is the key profibrotic cytokine in idiopathic pulmonary fibrosis (IPF), but the primary source of this cytokine in this disease is unknown." (PMID 37643008, 2023).
pulmonary fibrosis (continued). "The different time course of TGFβ1 expression during the process of BLM-induced lung fibrosis may explain the discrepancy between the protein and mRNA expression of TGFβ1." (PMID 37047672, 2023). "Moreover, this ion plays a crucial role in reducing airway hyper-reactivity and wheezing, and has the potential to prevent pulmonary fibrosis by reducing TGFb1 release, and subsequent intrapulmonary collagen deposition." (PMID 37376511, 2023). "Moreover, RGE prevented pulmonary fibrosis by regulating the transforming growth factor beta 1 (TGF-β1) pathway." (PMID 37686071, 2023). "Finally, we evaluated the expression of eleven CR-DEGs in a bleomycin-induced pulmonary fibrosis model and in TGFβ1-activated human lung fibroblasts." (PMID 37122736, 2023). "Finally, we established a mouse model of bleomycin-induced pulmonary fibrosis and a model of fibroblasts treated with TGFβ1." (PMID 37122736, 2023). "Studies that include mild to severe and critical cases are needed to confirm if the upregulation of TGFB1 enhances poor COVID-19 outcomes as may be pulmonary fibrosis development." (PMID 37389217, 2023). "Moreover, we validated hub gene expression levels by RT-qPCR in bleomycin-induced pulmonary fibrosis and a TGFβ1-induced cell model." (PMID 37122736, 2023). "Fibrosis-related genes include Col1a1, Acta2, Fn1, and Tgfb1 gene, and senescence-related genes composed of Cdkn2a, Tnf, Serpine1, Ccl2, Mmp10, and Mmp12 gene, all of which reflected the intensity of lung fibrosis and senescence events in lung tissue and pulmonary fibroblasts." (PMID 35662697, 2022). "The loss of AGER was caused by TGFB1 and TNF-alpha in the pulmonary fibrosis." (PMID 35185901, 2022). "In a bleomycin-induced pulmonary fibrosis rat model, epalrestat (an AR inhibitor) reduced fibrosis changes in the lung and prevented collagen deposition by decreasing expression and production of TGFβ1, α-smooth muscle actin (α-SMA), and type I collagen." (PMID 36235741, 2022). "We previously demonstrated that corisin induces AE of pulmonary fibrosis in TGFβ1 TG mice." (PMID 35322016, 2022). "We then allocated TGFβ1 TG mice with lung fibrosis into two groups with matched CT scores." (PMID 35322016, 2022). "BMP3 suppresses TGFβ1-induced myofibroblast differentiation in murine pulmonary fibrosis models." (PMID 35879352, 2022). "In this study, the results showed that miR-21promotes lung fibrosis, as well as TGFβ1-induced ECM over-synthesis, after binding of TGFβ1 to TGFβ1R1, which activates the SMAD2/3 complex and the nuclear entry of SMAD4, facts that regulate both miR-21 expression and ECM protein expression." (PMID 35743055, 2022). "Thus, intravenous MANPs enabled targeting of the population of profibrotic macrophages and delivery of TGFβ1 siRNA to prevent lung fibrosis and improve survival." (PMID 35377803, 2022). "To explore the relationship between ER stress and myofibroblast transformation of LR-MSC during lung fibrosis, we introduced TGFβ1, a classic profibrotic growth factor, and tunicamycin (TM) to induce myofibroblast transformation and ER stress of LR-MSC in vitro, respectively." (PMID 35765096, 2022). "TGFβ1 TG mice, with fibrosis, receiving corisin and treated with control IgG had deterioration of CT findings, whereas counterparts treated with anticorisin mAtb had significant amelioration of CT score of lung fibrosis." (PMID 35322016, 2022). "The main purpose of this study was to investigate the protective effect of THSG against bleomycin (BLM)-induced lung fibrosis in a murine model, and explore the underlying mechanisms of THSG in transforming growth factor-beta 1 (TGF-β1)-induced fibrogenesis using MRC-5 human lung fibroblast cells." (PMID 36267283, 2022). "Moreover, TGFβ1 was inversely correlated with CTSK expression during silica-induced lung fibrosis in mice." (PMID 33445732, 2021).
pulmonary fibrosis (continued). "H19 is upregulated via diminishing miR‐140 expression in fibrotic tissues from IPF patients and bleomycin‐induced pulmonary fibrosis in mice and TGFβ1‐induced HBE and A549 cells, in which the TGFβ/Smad3 signal pathway is involved in myofibroblast generation and extracellular matrix deposition." (PMID 33533071, 2021). "An example could be phenylbutyric acid (PBA), a chemical chaperone, which was found to inhibit EMT in the lungs, reduce the expression of pulmonary TGFβ1, and attenuate bleomycin-induced pulmonary fibrosis." (PMID 33803835, 2021). "Therefore, SAP seems to exert an anti-fibrotic effect in TGFβ1-induced lung fibrosis by regulating macrophage responses." (PMID 33670759, 2021). "Transforming growth factor β1 (TGFB1/TGFβ1) is the main pro-fibrotic cytokine in the progression of idiopathic pulmonary fibrosis, which induces lung fibroblasts to differentiate into myofibroblasts that produce high levels of collagen, resulting in a loss of lung elasticity and function." (PMID 33268902, 2021). "To further verify induction of PDCD5 expression in TGF-β-driven lung fibrosis, we next evaluated changes in PDCD5 expression in a transgenic mouse model with inducible overexpression of TGF-β1 (Ccsp-TGFβ1-TG mice), which induces lung fibrosis after administration of doxycycline (Dox)." (PMID 34011956, 2021). "Therefore, we evaluated the role of CRBN in bleomycin (BLM)-induced pulmonary fibrosis in mice and in transforming growth factor-beta 1 (TGF-β1)-induced differentiation of human lung fibroblasts." (PMID 34002012, 2021). "Moreover, iPSC transplantation blocked TGFβ1/Smad2/3 signaling, which is a key profibrotic pathway and potential therapeutic target in lung fibrosis." (PMID 34685439, 2021). "However, previous studies found that the combination of C3a and C3aR upregulated the expression of TGFβ1, and thereby promoted the progression of pulmonary fibrosis." (PMID 34433493, 2021). "We have used our human tissue model of early lung fibrosis to perform the first detailed analysis of the anti-fibrotic effects of pirfenidone and nintedanib in human lung tissue stimulated with the key pro-fibrotic growth factor TGFβ1." (PMID 34712131, 2021). "ERK1/2 and TGFβ1/Smad3 are two key signaling pathways that are involved in pulmonary fibrosis." (PMID 33747104, 2021). "And in our previous study, we identified bixin is a novel Nrf2 activator, which could suppress the NF-κB regulated inflammatory response and improve the lung fibrosis through inhibition of TGFβ1 signals in an Nrf2-dependent manner." (PMID 33603948, 2021). "Consistent with this previous evidence, here we found significant suppression of lung fibrosis (eg, collagen deposition area, Ashcroft and CT fibrosis score) and reduction of lung inflammation (lung cell inflammatory cells and cytokines) in TGFβ1-TG mice with pulmonary fibrosis treated with PFD." (PMID 33390975, 2020). "However, intranasal administration of TGFβ1-expressing plasmid results in increased TGFβ1- and IL-10-producing Treg cells and ameliorates bleomycin-induced lung fibrosis in mice." (PMID 32676074, 2020). "Therefore, here we used TG mice with lung fibrosis induced by lung overexpression of human TGFβ1, as previously reported." (PMID 32210242, 2020). "Here, we evaluated whether intrapulmonary delivery of PFD is therapeutically effective in TGFβ1-driven lung fibrosis." (PMID 33390975, 2020). "Our previous study demonstrated that bixin could protect against lung fibrosis by inhibiting the TGFβ1 signaling." (PMID 33313043, 2020). "TGFβ1/Smad3 signal pathway plays an important role in lung fibrosis and epithelial regeneration." (PMID 33101446, 2020). "Together, these results suggest that activation of AMPK by WEL followed by reduction in TGFβ1/Raf-MAPK signaling pathways may have a therapeutic potential in pulmonary fibrosis." (PMID 30890932, 2019).
pulmonary fibrosis (continued). "Moreover, they are protected from bleomycin-induced lung fibrosis, established as TGFβ1 dependent, and gene expression profiles of the β6−/− lungs show the majority of TGFβ responsive genes are not upregulated." (PMID 31438626, 2019). "We further investigated the effect of calpeptin on the expression of TGFβ1 in lung fibrosis." (PMID 29666896, 2018). "Given that TGFβ1 as a “master switch” in the development of EMT during the process of lung fibrosis, we explored whether calpeptin inhibited the expression of TGFβ1." (PMID 29666896, 2018). "Our study also found that calpeptin could suppress TGFβ1-Smad2/3 signaling pathway in lung fibrosis." (PMID 29666896, 2018). "Importantly, we confirm a role for Smad signalling in vivo using a TGFβ1-overexpression model of pulmonary fibrosis." (PMID 27494713, 2016). "Finally, using an adenoviral TGFβ1 over-expression model of pulmonary fibrosis we demonstrate that Smad3 is crucial for TGFβ1-induced αvβ6 integrin expression within the alveolar epithelium in vivo." (PMID 27494713, 2016). "For example, TGFB1 is an essential mediator of pulmonary fibrosis and can induce SPP1 expression." (PMID 26955063, 2016). "Markedly high Tgfb1 mRNA transcript levels were detected in sarcoid mice with lung fibrosis, suggesting that increased levels of TGF-β1 might play a role in the late stages of fibrosis induction." (PMID 27203210, 2016). "Finally, we evaluated the antifibrotic efficacy of TGFβ1-hypersecreting HBMSCs in a BLM-induced pulmonary fibrosis mouse model." (PMID 27107963, 2016). "In human patients with progressive pulmonary fibrosis, TGFB1-associated expression of fibroblastic PTK2 has been reported and experiments in a bleomycin-induced pulmonary fibrosis mouse model indicated that this kinase is related to fibroblastic proliferation, activation and collagen production." (PMID 27282780, 2016). "It is also clear that TGFβ1 is an important factor in the pathogenesis of pulmonary fibrosis." (PMID 26059457, 2015). "A key role for TGFβ1 in lung fibrosis has been confirmed in studies showing the development of lung fibrosis in animals transfected with TGFβ1-producing adenovirus, and by work demonstrating inhibition of experimental lung fibrosis by interventions targeting TGFβ1 or its downstream signals." (PMID 22997505, 2012). "It has been well-documented that TGFβ1 appears to be the predominant isoform of TGFβs involved in pulmonary fibrosis, which exerts its profibrotic effects through chemoattraction and stimulation of fibroblasts to express growth factors and extracellular matrix components." (PMID 19552800, 2009). "As a key factor of pulmonary fibrosis, TGFβ1 was determined by Western blot." (PMID 19552800, 2009). "Furthermore, the results of our earlier studies, a graphical representation of which is presented in the current manuscript, revealed that the range of pulmonary fibrosis correlated with the pulmonary level of TGFβ1—the best-known and best-described EMT inducer." (PMID 40860870, 2025). "Additionally, the consequent activation of transforming growth factor beta 1 (TGF-β1) by furin could worsen the injury of the lung by prompting the progression of pulmonary fibrosis, which is prevalent in intense COVID-19 cases." (PMID 39434774, 2024). "However, the regulatory mechanism in the upstream of TGFβ1 signalling during pulmonary fibrosis remains unclear." (PMID 37710230, 2023). "In addition, CC-11050 treatment significantly downregulated the expression of genes that play a key role in lung fibrosis, such as TGFB1 (16 dpi; p=0.0433), COL1A1 (16 dpi, p=0.009), TAGLN (16 dpi; p=0.0218), MYH11 (4 dpi; p=0.0042; 16 dpi; p=0.05) and SMAD2 (16 dpi; p=0.008)." (PMID 37854602, 2023).